EPHB4 (EPH receptor B4)
Diseases named in the same sentence as EPHB4 in open-access papers (continued):
Sharing a sentence is not in itself a finding about the gene and the disease.
ovarian carcinoma (continued). "Among the invasive ovarian cancers, 73 (86%) expressed EphB4 and moderate or strong expression was noted in 49 (58%) samples." (PMID 17353927, 2007). "Taken together, these results establish EphB4 as a novel target for biological therapy in ovarian cancer." (PMID 17353927, 2007). "The coexpression of EphB4/ephrinB2 may potentiate tumour advancement leading to poor survival and can be recognised as a novel prognostic indicator in the primary tumour of ovarian cancers." (PMID 18231102, 2008). "EphB4 and ephrinB2 were dominantly localised in ovarian cancer cells of all cases studied." (PMID 18231102, 2008). "Thus, EphB4/ephrinB2 can be recognised as a novel prognostic indicator in the primary tumours of ovarian cancers." (PMID 18231102, 2008). "Hence, EphB4 affords a malignant phenotype to ovarian cancer cells by favouring tumour cell migration and invasion, independent of its direct prosurvival signals." (PMID 17353927, 2007). "Thus, EphB4 confers to ovarian cancer cells the ability to migrate and invade basement membranes, known characteristics of an aggressive malignancy." (PMID 17353927, 2007). "We wanted to determine the biological role of EphB4 in ovarian cancer." (PMID 17353927, 2007). "We were thus interested in understanding the biological role played by EphB4 in ovarian cancer." (PMID 17353927, 2007). "EphB4 expression may thus be a prognostic marker for outcome and response to therapy in ovarian cancer." (PMID 17353927, 2007). "Thus, we report a novel EphB4-based therapeutic approach against ovarian cancer." (PMID 31949258, 2020). "Thus, data from our present study suggest that autocrine stimulation by EphB4 and ephrinB2 coexpression might mediate the advancement of ovarian cancer." (PMID 18231102, 2008). "Furthermore, all five ovarian carcinoma cell lines express EphB4." (PMID 17353927, 2007). "Therefore, targeting EphB4 may have a dual benefit in ovarian cancer – abolishing direct tumour cell antiapoptotic signals and inhibiting tumour vascularisation." (PMID 17353927, 2007). "Inhibition of EphB4 may hence have prognostic and therapeutic utility in ovarian carcinoma." (PMID 17353927, 2007). "While the exact resistance mechanism has not yet been determined, EphB4 is overexpressed in bevacizumab-resistant ovarian cancer SKOV3 xenograft and co-administration of bevacizumab with the EphB4 blocker, NVP-BHG712, results in reversal of resistance and inhibition of tumor growth." (PMID 35800369, 2022). "Next, we determined the phosphorylation of EphB4 and its downstream adaptor protein Crk1 (MAPK14) in lysates from human A2780cp20 ovarian cancer cells by immunoprecipitation with anti-EphB4 and anti-Crk1 antibodies followed by immunoblotting with phospho-specific antibodies." (PMID 31949258, 2020). "We show that EphB4 is overexpressed in a vast majority of ovarian cancers, with minimal or no expression in normal ovarian epithelium." (PMID 17353927, 2007). "EphB4 expression was largely absent in normal ovarian surface epithelium, but was expressed in 86% of ovarian cancers." (PMID 17353927, 2007).
arteriovenous malformation (11 papers, 2013 to 2026). "The ratio of ephrinB2 to EphB4 expression is disturbed at both mRNA and protein level in ECs cultured from patient arteriovenous malformations, with greatly reduced EphB4 expression compared with a control cell line." (PMID 34403370, 2021). "The EphrinB2/EphB4 signaling and notch pathway are involved in the pathogenesis of Arteriovenous Malformation (AVM), suggesting the direct genetic connection between the arterial-venous specification and CM-AVM/AVM." (PMID 23663822, 2013).
head and neck squamous cell carcinoma (11 papers, 2010 to 2025). A squamous cell carcinoma that arises from any of the following anatomic sites: lip and oral cavity, nasal cavity, paranasal sinuses, pharynx, larynx, and salivary glands. "Our emerging understanding of the dichotomous roles that EphB4 and ephrinB2 play in head and neck squamous cell carcinoma (HNSCC) poses a significant challenge to rational drug design." (PMID 39091728, 2024). "Here, we interrogate the effects of targeting EphB4 and ephrinB2 in head and neck squamous cell carcinoma (HNSCC) and within its microenvironment using genetically engineered mice, recombinant constructs, pharmacologic agonists and antagonists." (PMID 35725568, 2022). "In contrast, in head and neck squamous cell carcinoma (HNSCC), a different Eph receptor is implicated, EphB4." (PMID 36175961, 2022). "EphB4 siRNA significantly inhibited tumor cell viability, induced apoptosis, activated caspase-8, and inhibited the growth of tumor xenografts in vivo in head and neck squamous cell carcinoma." (PMID 32733636, 2020). "We used orthotopic models of head and neck squamous cell carcinoma to determine the role of EphB4-ephrin-B2 interaction in tumor immune microenvironment." (PMID 30400822, 2018). "EphB4 knockdown has been shown to increase the expression of apoptotic proteins, including Bax and caspase-3, suggesting its potential role in promoting growth and invasion in head and neck squamous cell carcinoma." (PMID 40181975, 2025). "Moreover, EphB4 and ephrinB2 gained increasing attention with regard to therapy resistance in different solid tumors such as head and neck squamous cell carcinoma (HNSCC), pancreatic adenocarcinoma (PDAC), and bladder urothelial carcinoma." (PMID 33153234, 2020). "Moreover, the overexpression of EphB4 and EFNB2 is associated with poor prognosis in head and neck squamous cell carcinoma patients and may serve as valuable prognostic markers." (PMID 40181975, 2025). "EphrinB2 and its receptor EphB4 are highly expressed in head and neck squamous cell carcinoma (HNSCC) and disrupting EphB4-ephrinB2 interaction generates sub-optimal outcomes." (PMID 35725568, 2022). "Preclinical and clinical studies have investigated the use of EphB4-Human Serum Albumin Fusion Protein (sEphB4-HAS) in the treatment of cancer, particularly head and neck squamous cell carcinoma (HNSCC)." (PMID 40421081, 2025).
hepatocellular carcinoma (10 papers, 2014 to 2025). A malignant tumor that arises from hepatocytes. "For shRNA, lentiviral vectors (Lv) Lv-shRNA-EphB4 were used to transfect and knockdown erythropoietin-producing hepatocellular carcinoma receptors B4 (EphB4)." (PMID 41155961, 2025). "HHT restrains tumor progression by inhibiting some oncoproteins in various malignancies, such as EphB4 in hepatocellular carcinoma, PHGDH in neuroblastoma, and NF-κB in acute myelogenous leukemia." (PMID 38770133, 2024). "In this study, our research was aimed at exploring the embedded mechanism on molecules of miR-130-3p-EPHB4 in terms of transfer of MTX-induced immunogenicity in hepatocellular carcinoma cells, as well as providing any potential effective targets of therapy for PC treatment." (PMID 34336153, 2021). "In summary, our results confirm that miR-130-3p inhibits the proliferation and migration of HCC cells by targeting EPHB4 and induces immune death of hepatocellular carcinoma cells by promoting drug." (PMID 34336153, 2021).
esophageal cancer (8 papers, 2016 to 2025). A primary or metastatic malignant neoplasm involving the esophagus. "Bioinformatic analyzes using the Oncomine platform revealed a dramatic increase in EphB1, EphB2, and EphB4 in esophageal cancer, suggesting these receptors as potential biomarkers." (PMID 39839790, 2024). "Moreover, in a tumor cell xenograft model, a significant reduction in tumor volume was observed after treatment with an EphB4 inhibitor, reinforcing its effectiveness as a new biomarker and molecular target for esophageal cancer." (PMID 39839790, 2024). "For example, the aberrant interaction of epithelial cells within the basal layer at early precancerous stage involves Ephrin-B1 (EFNB1) –Eph receptor B4 (EPHB4) which triggers EMT, leading to esophageal cancer tumorigenesis and progression." (PMID 40248695, 2025).
glioblastoma (8 papers, 2014 to 2024). The most malignant astrocytic tumor (WHO grade IV). "The results revealed that EphA2, EphB2, EphB3, and EphB4 were significantly upregulated, while EphA4 and EphB6 were significantly downregulated in glioblastoma than normal brain tissues, respectively." (PMID 37146061, 2023). "In glioblastoma cell lines, EPHB4, along with its ligand, ephrin-B2, were observed to enhance angiogenesis through interacting with VGFR2 and Notch signaling pathways." (PMID 34445116, 2021). "In human glioblastoma multiforme patients, high EphB4 expression correlates with decreased progression-free survival underlining a more aggressive phenotype." (PMID 29987450, 2018). "Eight circRNAs, including circ_COL1A2, circ_PTN, circ_VCAN, circ_SMO, circ_PLOD2, circ_GLIS3, circ_EPHB4, and circ_CLIP2 showed significantly higher expression in glioblastoma (GBM) than in normal tissues." (PMID 28969099, 2017). "For example, EphB4-binding peptide and synthetic somatostatin analogue of octreotide-conjugated CCPMs were prepared to detect EphB4-positive PC-3 M prostate and somatostatin receptor overexpressed glioblastoma U87 cells, respectively." (PMID 25379530, 2014). "The expression levels of circ_COL1A2, circ_PTN, circ_VCAN, circ_PLOD2, circ_SMO, circ_CLIP2, circ_GLIS3, and circ_EPHB4 in glioblastoma (GBM) are significantly higher than those in normal tissues." (PMID 30064463, 2018). "Therefore, it was supported that C35 is capable of selectively binding to EphB4-expressing angiogenic blood vessels and EphB4-expressing tumor cells, rendering it an appealing bioimaging agent for both PET/CT and optical imaging of glioblastoma." (PMID 39518106, 2024).
rhabdomyosarcoma (8 papers, 2017 to 2025). A rare aggressive malignant mesenchymal neoplasm arising from skeletal muscle. "EPHB4 expression in malignant bone and soft-tissue tumors, particularly rhabdomyosarcoma, has been suggested to be associated with prognosis." (PMID 40842575, 2025). "An increased expression of EPHs (EPHB1, EPHB2, EPHB3, and EPHB4) and their ephrin ligands (ephrin-B1 and ephrin-B2) has been implicated in promoting angiogenesis and tumor progression in rhabdomyosarcoma." (PMID 38612645, 2024). "Ligand-independent activation of EPHB4 causes cell proliferation and malignant transformation in rhabdomyosarcoma, whereas ligand-dependent stimulation of EPHB4 induces apoptosis in rhabdomyosarcoma." (PMID 33816783, 2021). "EPHB4-CAR-T cells also demonstrated potent and durable efficacy against EPHB4-positive RH30 rhabdomyosarcoma cells." (PMID 40842575, 2025). "Neuroblastoma, medulloblastoma, and rhabdomyosarcoma are characterized by increased EPHB4 expression, while T-ALL presents enhanced EPHB6 expression." (PMID 38612645, 2024). "EPHB4, specifically, has been highlighted as a potential therapeutic target for alveolar rhabdomyosarcoma, with studies suggesting its role as a poor prognostic indicator in certain cell lines (especially A203, RD-ES, and A673)." (PMID 38612645, 2024). "Engineered EPHB4-CAR-T cells showed sustained killing activity against osteosarcoma as well as against rhabdomyosarcoma cell lines, even for PAX3-FOXO1-positive ARMS cells, which exhibit highly malignant immunomodulatory effects." (PMID 35563562, 2022). "Ephrin type-B receptor 4 (EPHB4), expressed in tumors including rhabdomyosarcoma, is a suitable target for chimeric antigen receptor (CAR)-T cells." (PMID 33816783, 2021). "Ephrin type-B receptor 4 (EPHB4) is widely expressed in many tumor types, including rhabdomyosarcoma (RMS)." (PMID 35011583, 2021). "EphB4 has a role in tumorigenesis and the metastatic process of synovial sarcoma and the alveolar subtype of rhabdomyosarcoma." (PMID 34440844, 2021). "Although the role of Eph proteins in rhabdomyosarcoma has been largely uncharacterized until recently, earlier reports have affirmed upregulation of Ephrin receptor B4 (EphB4) and its cognate ligand EphrinB2 in aRMS." (PMID 28817624, 2017). "Previously, we have demonstrated that EphB4 and EphrinB2 are both expressed in the alveolar subtype of rhabdomyosarcoma (aRMS)." (PMID 28817624, 2017). "Considering the positive correlation between EphB4 expression and patient survival, we wanted to determine if EphB4 forward signaling inhibition was therapeutically contraindicated in the embryonal rhabdomyosarcoma subtype." (PMID 28817624, 2017). "Similarly, these oncogenic effects are demonstrated in soft tissue sarcomas when EPHA3, EPHB2 and EPHB4 stimulate properties such as proliferation, increased motility, migration, invasion and metastasis of rhabdomyosarcoma and synovial sarcoma cells." (PMID 35563562, 2022). "piggyBac transposon-mediated CAR-T cell therapy targeting EPHB4 exhibited sufficient CAR positivity, stable CAR expression, a favorable phenotype, and strong antitumor efficacy against EPHB4-positive tumors and would be promising for the treatment of malignant rhabdomyosarcomas." (PMID 33816783, 2021). "EphB4 and its ligand EphrinB2 are both expressed in the alveolar subtype of rhabdomyosarcoma." (PMID 34440844, 2021). "Therefore, PB-EPHB4-CAR-T cells possess a memory-rich fraction without early T cell exhaustion and show potential as promising therapeutic agents for treating rhabdomyosarcoma and other EPHB4-positive tumors." (PMID 33816783, 2021). "EPHB4-CAR-T cells were created via piggyBac (PB) transposon-based gene transfer and exhibited antitumor efficacy against EPHB4-positive rhabdomyosarcoma tumors." (PMID 35563562, 2022).
rhabdomyosarcoma (continued). "Interestingly, as it is observed for the case of EPHB4, the same EPH can exert either a pro-tumorigenic (i.e., in neuroblastoma and rhabdomyosarcoma) or anti-tumorigenic function (i.e., in ALL) depending on the type of neoplasm it is expressed." (PMID 38612645, 2024). "We conclude that inhibition of EphB4 signaling with these agents is not a viable monotherapy for rhabdomyosarcoma." (PMID 28817624, 2017). "Therefore, we queried the Intergroup Rhabdomyosarcoma Study Group (IRSG)-IV Affymetrix U95 GeneChip database for expression of EphB4 in human eRMS and uncovered that elevated EphB4 expression correlates with a positive prognosis for eRMS patients." (PMID 28817624, 2017). "Indeed, direct EphB4 inhibition using the humanized inhibitory antibody VasG3 failed to affect tumor growth and survival rates in alveolar rhabdomyosarcoma cells xenograft models." (PMID 34440844, 2021). "Therefore, we hypothesized that ligand-based, EPHB4-specific CAR-T cells may kill rhabdomyosarcoma cells without stimulating downstream cell proliferation mechanisms." (PMID 33816783, 2021).
sarcoma (8 papers, 2016 to 2025). A usually aggressive malignant neoplasm of the soft tissue or bone. "We performed immunohistochemical assays for EphB4 and EphrinB2 expression on neuroblastoma tissue microarrays (TMAs) as well as osteosarcoma TMAs, which were then scored by a sarcoma pathologist (AM)." (PMID 28817624, 2017). "Recent evidence suggests involvement of RTKs such as PDGFR, c-Met, Axl, IGF1-R, EphB4 and ErbB4 as driver kinases in different sarcoma subtypes including synovial sarcoma, Ewing sarcoma as well as malignant peripheral nerve sheath tumor (MPNST)." (PMID 26675259, 2016). "However, Eph and IGF1 signaling pathways cross-talk to regulate bone and skeletal muscle cells function and EphA2 and EphB4 exert oncogenic effects in different types of sarcomas, supporting the rationale for targeting Eph-dependent pathways in those tumors." (PMID 34440844, 2021). "EphB4 expression was too essentially higher in delicate tissue sarcomas, and mRNA and protein expression were altogether expanded in synovial sarcomas, while the regulation mechanism of EPHB4 still remains unknown." (PMID 34336153, 2021).
vascular malformation (8 papers, 2021 to 2025). A non-neoplastic disorder that is the result of defects of vascular morphogenesis. "Regarding the EPHB4 gene, it encodes a guidance molecule involved in endothelial cell progenitor migration and differentiation, and defects in its expression can cause vascular malformations in arteries, veins, and lymphatic vessels." (PMID 38203852, 2024). "Our findings reveal how Eph-ephrin interactions integrate cell segregation and arteriovenous specification in the vasculature, which has potential relevance for human vascular malformations caused by EPHB4 mutations." (PMID 38570531, 2024). "First, we performed manual analysis and variant calling of the sequencing data for the genes known to cause HHT (ACVRL1, ENG, GDF2, SMAD4) or vascular malformation syndromes with similar phenotypes (EPHB4, RASA1), as well as PIK3CA, which has been shown to modify vascular malformation phenotypes." (PMID 39062925, 2024). "Genetic analyses of ACVRL1, ENG, and SMAD4 (in addition to EPHB4 and RASA1) are considered reasonable in all cases of high-flow intracerebral vascular malformations regardless of other HHT signs." (PMID 40259928, 2025).
head and neck cancer (7 papers, 2007 to 2025). A primary or metastatic malignant neoplasm affecting the head and neck. "A recent study showed that blocking EFNB2/EPHB4 signaling increased the response to cetuximab-radiation therapy in head and neck cancers." (PMID 36376513, 2023). "Soluble EphB4-albumin blocks bidirectional signalling between EphB4 and Ephrin B2 and was well tolerated when administered to patients with head and neck cancer." (PMID 36831514, 2023). "Elevated expression of EPHA4 was found in head and neck cancers, although differential outcomes of EphB4-ephrinB2 (its ligand) signaling have been reported in these neoplasms." (PMID 36362284, 2022). "Overall, our findings emphasize the therapeutic relevance of EphB4 targeting as a radiosensitizer that can be exploited for the treatment of human head and neck carcinomas." (PMID 27941840, 2016). "We have shown in breast and head and neck cancer cells that the extracellular domain of EphB4 is capable of protecting tumour cells from TRAIL-induced apoptosis." (PMID 17353927, 2007). "We have shown recently such a role of EphB4 in prostate, bladder, breast, and head and neck cancers." (PMID 17353927, 2007). "In conclusion, our data suggest that EphB4 serves as an ideal target and EphB4-directed therapeutic agents in combination with radiation may hold a great promise for clinical translation in head and neck cancer." (PMID 27941840, 2016). "EphB4 is similarly over-expressed in head and neck cancers (100% of 37 cases examined) and knockout studies using siRNA and antisense both in vitro and importantly, in vivo, have demonstrated that EphB4 has an essential role in many processes that contribute to cancer cell survival and spread." (PMID 19961621, 2009).